STOX1 (storkhead box 1)
Diseases named in the same sentence as STOX1 in open-access papers (continued):
Sharing a sentence is not in itself a finding about the gene and the disease.
Hypertension (8 papers, 2008 to 2025). The presence of chronic increased pressure in the systemic arterial system. "Whether abnormalities in Stox1-KO placentas arose as a direct consequence of STOX1 deficiency, or secondary to renin-induced hypertension or other pathophysiology, is uncertain." (PMID 33301424, 2021). "Third, overexpression of the transcription factor Storkhead box 1 (STOX1) led to PE symptoms in pregnant mice, including hypertension, proteinuria and structural impairments of kidneys and placenta." (PMID 33746781, 2021).
Alzheimer disease (5 papers, 2014 to 2025). A progressive, neurodegenerative disease characterized by loss of function and death of nerve cells in several areas of the brain leading to loss of cognitive function such as memory and language. "Notably, CNTNAP2 expression is decreased in the hippocampus of Alzheimer’s disease (AD) patients due to the downregulation by STOX1, supporting the association between CNTNAP2 level and memory." (PMID 37089693, 2023). "Furthermore, STOX1 was found to be overexpressed and associated with Alzheimer's disease, and studies have shown that STOX1 may control a conserved pathway shared between the placenta and the brain." (PMID 31724315, 2020). "Other genes mapping in the deleted region, including DNAJC12 (MIM 606060), HERC4 (MIM 609248), PBLD (MIM 612189), HNRNPH3 (MIM 602324), RUFY2 (MIM 610328), STOX1 (MIM 609397), and CTNNA3 (MIM 607667), have been linked to late-onset Alzheimer’s disease (AD6; MIM 605526)." (PMID 24297458, 2014).
glioma (5 papers, 2021 to 2025). A benign or malignant brain and spinal cord tumor that arises from glial cells (astrocytes, oligodendrocytes, ependymal cells). "Next we evaluated the association between STOX1 expression and clinicopathologic features of glioma patients in CGGA and TCGA using the Pearson’s chi-square test." (PMID 34722888, 2021). "In the present study, the association between STOX1 expression and prognosis of glioma patients were evaluated based on the CGGA, TCGA, and Rembrandt datasets." (PMID 34722888, 2021). "We also found that low expression of STOX1 was more often found in IDH1 wild-type gliomas, suggesting that STOX1 may be functionally associated with IDH1 status." (PMID 34722888, 2021). "Interestingly, the STOX1 gene loci is close to these tumor suppressors on chromosome 10, and one may infer that grade-dependent downregulation of STOX1 in glioma may result from loss of heterogeneity." (PMID 34722888, 2021). "However, the expression profiles of STOX1, its association with clinicopathological characteristics, and potential functions in glioma remain unknown." (PMID 34722888, 2021). "In the context of cancer, limited research has reported STOX1 overexpression in colon adenocarcinoma and its downregulation in medulloblastoma and glioma." (PMID 40567110, 2025). "STOX1 expression in glioma was analyzed using three publicly available datasets, including CGGA, TCGA, and Rembrandt." (PMID 37047356, 2023). "To further determine the STOX1 expression pattern in glioma, we analyzed STOX1 expression in different histological types of gliomas in each dataset." (PMID 34722888, 2021). "Further investigations on the functional roles and therapeutic value of STOX1 in glioma are warranted." (PMID 34722888, 2021). "Further multivariate Cox regression analyses revealed that STOX1 downregulation predicted shorter overall survival of glioma patients (HR: 0.731, 95% CI: 0.542–0.987, and P = 0.041 in CGGA and HR: 0.719, 95% CI: 0.469–1.104, and P = 0.132 in TCGA)." (PMID 34722888, 2021). "In this study, we analyzed three publicly available datasets including CGGA, TCGA, and Rembrandt and revealed a grade-dependent reduction in STOX1 expression in glioma (P < 0.001)." (PMID 34722888, 2021). "Altogether, these data suggested that the expression of STOX1 was significantly downregulated in high-grade gliomas and that low expression of STOX1 correlated with the glioma malignancy." (PMID 34722888, 2021). "Notably, STOX1 downregulation has been associated with advanced WHO grades and poorer outcomes in glioma, suggesting its potential as a prognostic biomarker." (PMID 40567110, 2025). "Storkhead box 1 (STOX1) is an independent prognostic factor of glioma patients." (PMID 36814293, 2023). "Considering both glioma types and GB alone, patients with high-level STOX1 expression had a significantly higher OS than those with low-level STOX1 expression did, after analysis of both the Chinese Glioma Genome Atlas (CGGA) and The Cancer Genome Atlas (TCGA) datasets." (PMID 37047356, 2023). "To our knowledge, this is the first time to report STOX1 expression and its prognostic value in cancer, and we infer that STOX1 may function as a tumor suppressor in glioma." (PMID 34722888, 2021). "Moreover, STOX1 expression was also found to be significantly higher in all IDH1-mutant gliomas in TCGA and GBMs in CGGA compared with their IDH1 wild-type counterparts." (PMID 34722888, 2021). "We found that low STOX1 expression would predict a higher degree of glioma malignancy and worse overall patient survival, and that STOX1 may serve as a potential molecular target for glioma." (PMID 34722888, 2021). "Taken together, these findings suggested that STOX1 may be used as a novel predictive molecular biomarker for glioma grading and overall patient survival." (PMID 34722888, 2021).
glioma (continued). "The signaling pathways that may involve STOX1 and which are relevant to glioma pathogenesis were analyzed through GSEA." (PMID 34722888, 2021). "Altogether, all these enriched gene sets are related to cancer and further investigation on the mechanistic relationships between STOX1 and these pathways could provide novel insights into the pathogenesis and treatment of glioma." (PMID 34722888, 2021). "In this study, we, for the first time, explore the expression profile and prognostic value of STOX1 in glioma patients using public datasets including the Chinese Glioma Genome Atlas (CGGA), The Cancer Genome Atlas (TCGA), and Repository of Molecular Brain Neoplasia Data (Rembrandt)." (PMID 34722888, 2021). "This study, through the analysis of several database data, for the first time provides comprehensive evidence that STOX1 is downregulated in high-grade gliomas, correlates with glioma grade, and might serve as an independent prognostic biomarker for glioma patients." (PMID 34722888, 2021). "Moreover, multivariate Cox regression analysis showed that STOX1 expression may serve as a novel independent prognostic biomarker in glioma patients." (PMID 34722888, 2021). "Low STOX1 expression could also independently predict a worse prognosis in glioma patients." (PMID 34722888, 2021). "Other mitochondrial oxidative-stress-related genes including CTSL, TXNRD2, NUDT1, STOX1, and CYP2E1 have been reported differentially expressed with potential prediction accuracy of glioma." (PMID 39012280, 2024). "However, the role of STOX1 in glioma remain largely unknown." (PMID 34722888, 2021). "Second, protein expression levels of STOX1 in gliomas were not investigated due to insufficient glioma specimens in our hospital." (PMID 34722888, 2021). "First, due to the lack of glioma transcriptome datasets which distinguish the expression profiles of STOX1 transcript isoforms, STOX1 was considered as a single entity in the current study." (PMID 34722888, 2021). "Patients with high expression of STOX1 had significantly longer OS than those with low STOX1 expression in all gliomas or GBM cohort alone in both CGGA (All gliomas, P < 0.001 and GBM, P = 0.007) and TCGA (All gliomas, P < 0.001 and GBM, P = 0.018) datasets." (PMID 34722888, 2021). "Moreover, we found that low expression of STOX1 was more frequently present in 1p/19q codeleted gliomas in TCGA but not in CGGA." (PMID 34722888, 2021). "STOX1 may be one of the negative modulators of glioma and downregulation of STOX1 may lead to the malignant progression of glioma." (PMID 34722888, 2021). "Although the roles of STOX1 in glioma have not yet been clarified, our study predicts that STOX1 may be used as a biomarker to assist in the diagnosis and treatment of glioma, and it could also be used as a prognostic marker for glioma patients." (PMID 34722888, 2021). "We showed that STOX1 expression was downregulated in high-grade (Grades III and IV) gliomas but not in Grade II tumors when compared to nontumor brain tissues and exhibited a grade-dependent decrease in all gliomas." (PMID 34722888, 2021).
endothelial dysfunction (3 papers, 2015 to 2025). In vascular diseases, endothelial dysfunction is a systemic pathological state of the endothelium (the inner lining of blood vessels) and can be broadly defined as an imbalance between vasodilating and vasoconstricting substances produced by (or acting on) the endothelium. "Endothelial dysfunction has been linked to overexpression of storkhead-box protein 1 (STOX1) by the fetoplacental unit." (PMID 41021586, 2025). "Finally, storkhead box 1 (STOX1) overexpression switches the free radical balance from reactive oxygen species to reactive nitrogen species in the placenta, which may deprive maternal NO and compromise blood flow or increase endothelial dysfunction." (PMID 25303561, 2015).
intrauterine growth restriction (3 papers, 2018 to 2022). "And, this study has reported that overexpression of STOX1 in placenta induced a switch between nitrosative and oxidative stress and intrauterine growth restriction." (PMID 31724315, 2020). "NODAL is located in the same chromosomal linkage area as the Dutch PE susceptibility gene STOX1, a transcription factor which is associated with the familial form of early-onset, IUGR (intrauterine growth restriction)-complicated PE." (PMID 30092105, 2018).
medulloblastoma (3 papers, 2020 to 2025). A malignant, invasive embryonal neoplasm arising from the cerebellum. "In addition, STOX1 was identified as a transcriptional suppressor that has a pivotal role in the cerebellar granule neurogenesis and medulloblastoma formation." (PMID 31724315, 2020).
HELLP syndrome (2 papers, 2013 to 2024). A life-threatening condition that can potentially complicate pregnancy. "Secondly, the genes identified by genome-wide linkage studies to be associated with pre-eclampsia (ACVR2A, STOX1) and the HELLP-syndrome (LINC-HELLP) are discussed regarding their potential functions in the etiology of disease." (PMID 24058367, 2013).
neuroblastoma (2 papers, 2021 to 2023). Neuroblastoma (NB) is the most common solid, extracranial childhood tumor. "In other words, rs3998860 and rs12781492 may affect neuroblastoma susceptibility and prognosis by influencing STOX1 mRNA expression." (PMID 37347215, 2023). "Our study reveals the unique cancer‐promoting effect of STOX1 in neuroblastoma compared to other tumours." (PMID 37347215, 2023). "Neuroblastoma patients with high STOX1 (n = 249) mRNA expression had significantly (p = 0.039) lower OS than neuroblastoma patients with low STOX1 mRNA expression (n = 249)." (PMID 37347215, 2023). "Based on the significant impact of rs3998860 and rs12781492 on STOX1 mRNA expression in the adrenal gland and whole blood, we further analysed the relationship between mRNA expression of STOX1 and prognosis of neuroblastoma through the R2: Genomics Analysis and Visualization Platform." (PMID 37347215, 2023). "However, another study reported that STOX1A played a tumor-promoting role in human neuroblastoma cell SH-SY5Y and favored mitotic entry by binding directly to Cyclin B1 promoter, suggesting that STOX1 may promote or suppress malignancy depending on tumor cell types." (PMID 34722888, 2021).
Obesity (2 papers, 2021 to 2026). Accumulation of substantial excess body fat. "Collectively, these findings indicate that decreased serum STOX1 tracks adverse metabolic and inflammatory profiles in obesity and support its potential utility as a noninvasive biomarker of adipose tissue inflammation in overweight/obese individuals." (PMID 41660420, 2026).
abortion (1 paper, 2018). the ending of pregnancy by removing a fetus or embryo before it can survive outside the uterus. "However, the effect and detailed mechanism of storkhead box 1 (STOX1) in recurrent spontaneous abortion (RSA) remain unknown." (PMID 30548667, 2018).
astrocytomas (1 paper, 2021). "We compared STOX1 expression of IDH1 wild-type GBMs with IDH1 wild-type astrocytomas and IDH1-mutant GBMs with IDH1-mutant astrocytomas." (PMID 34722888, 2021). "The results revealed that STOX1 expression in IDH1 wild-type GBMs was significantly lower than that of IDH1 wild-type astrocytomas in both datasets (Figure A1a and b)." (PMID 34722888, 2021). "Furthermore, in IDH1-mutant GBMs, STOX1 was significantly downregulated compared to IDH1-mutant astrocytomas (Figure A1c and d)." (PMID 34722888, 2021).
placental diseases (1 paper, 2008). "Very similar results were obtained when comparing STOX1 effects with transcriptional deregulation observed in older transcriptomic studies dealing with syncytialisation and the links between hypoxia and placental diseases." (PMID 19079545, 2008).
pregnancy diseases (1 paper, 2024). "Certain variants of the STOX1 transcription factor have been linked to pregnancy diseases, particularly hypertensive disorders of pregnancy." (PMID 38439971, 2024).
cancer (4 papers, 2021 to 2025). A tumor composed of atypical neoplastic, often pleomorphic cells that invade other tissues. "Among the upregulated genes were those linked to cancer formation (e.g., STOX1, PEG3, XIAP) and immune cell recruitment (e.g., CCL28, VIM), suggesting a shift towards increased cellular proliferation and remodelling of the immune microenvironment." (PMID 40683913, 2025). "However, to our knowledge, no studies have investigated the specific isoforms of STOX1, nor their clinical relevance or functional roles in cancer." (PMID 40567110, 2025).
tumours (4 papers, 2016 to 2025). "Early FDIM showed upregulation of genes linked to tumour initiation, immune recruitment, and motility (e.g., STOX1, PEG3, XIAP, MCAM, VIM)." (PMID 40683913, 2025). "STOX1 expression showed a grade-dependent reduction (II vs III, P < 0.001; II vs IV, P < 0.001; and III vs IV, P = 0.019) as tumor grade increases." (PMID 34722888, 2021).
STOX1 also shares sentences with these, for which no sentence is quoted: cardiac hypertrophy (1 paper); colon adenocarcinoma (1); colon cancer (1); dilated cardiomyopathy (1); hepatocellular carcinoma (1); late-onset Alzheimers disease (1); lumbar disc herniation (1); malignant glioma (1); oligodendroglioma (1); type 2 diabetes mellitus (1).